ATXN8 (ataxin 8)
Gene: Gene on chromosome 13 (70,137,831 to 70,139,431, reverse strand). Ensembl gene ENSG00000288330.
Subcellular location: Nucleus
Diseases named in the same sentence as ATXN8 in open-access papers:
ATXN8 is named in the same sentence as 14 diseases in open-access papers, as found by Europe PMC text mining. Sharing a sentence is not in itself a finding about the gene and the disease. The quoted sentences say what the papers report.
spinocerebellar ataxia type 8 (13 papers, 2009 to 2025). Spinocerebellar ataxia type 8 (SCA8) is a subtype of type I autosomal dominant cerebellar ataxia (ADCA type I) characterized by cerebellar ataxia and cognitive dysfunction in almost three quarters of patients and pyramidal and sensory signs in approximately a third of patients. "Spinocerebellar ataxia type 8 (SCA8) is an autosomal dominant neurodegenerative disease caused by non-coding CTA/CTG repeat expansions in ATXN8OS (ataxin 8 opposite strand)." (PMID 40765612, 2025). "RAN translation was originally described for CAG/CTG repeat expansions within the coding region of the ATXN8/ATXN8PS gene associated with the neurodegenerative disorder spinocerebellar ataxia type 8 (SCA8)." (PMID 30808398, 2019). "Spinocerebellar ataxia type 8 (SCA8) is a microsatellite expansion disorder caused by a bidirectionally transcribed CTG•CAG repeat expansion mutation within the ATXN8OS/ATXN8 genes." (PMID 34632710, 2021). "This non-canonical translational initiation process was discovered through the study of CAG trinucleotide expansions in the ATXN8 gene, which causes the neurodegenerative disorder spinocerebellar ataxia type 8 (SCA8)." (PMID 32777047, 2020). "This study shows CCG•CGG interruptions within the ATXN8OS/ATXN8 CTG•CAG repeat are an important genetic modifier of disease penetrance in spinocerebellar ataxia type 8 (SCA8)." (PMID 34632710, 2021). "Spinocerebellar ataxia type 8 (SCA8), a kind of slowly progressive ataxia, is caused by the abnormal expansion of (CTG)n within the responsible gene ATXN8." (PMID 30046585, 2018). "Bi-directional expression of the spinocerebellar ataxia type 8 (SCA8) CTG CAG expansion produces CUG expansion RNAs (CUGexp) from the ATXN8OS gene and a nearly pure polyglutamine expansion protein encoded by ATXN8 CAGexp transcripts expressed in the opposite direction." (PMID 19680539, 2009). "RAN translation was discovered by pioneering work in Spinocerebellar Ataxia Type 8 (SCA8) after the mutation of the ATG initiation codon in the CAG-repeat containing ATXN8 gene did not block the expression of the polyglutamine (polyQ) repeat in transfected cells." (PMID 35406787, 2022). "Spinocerebellar ataxia type 8 (SCA8) is a dominantly inherited, slowly progressive neurodegenerative disorder caused by the expansion of CTA/CTG combined repeats (CR) in the ataxin 8 opposite strand (ATXN8OS) gene located on chromosome 13q21." (PMID 19203395, 2009). "Spinocerebellar ataxia type 8 (SCA8) involves the expansion of CTG/CAG repeats from the overlapping ataxin 8 opposite strand (ATXN8OS) and ataxin 8 (ATXN8) genes located on chromosome 13q21." (PMID 24040107, 2013). "Spinocerebellar ataxia type 8 (SCA8) involves the expression of an expanded CTG/CAG combined repeats (CR) from opposite strands producing CUG expansion transcripts (ataxin 8 opposite strand, ATXN8OS) and a polyglutamine expansion protein (ataxin 8, ATXN8)." (PMID 19203395, 2009).
Ataxia (2 papers, 2013 to 2021). Ataxia refers to impaired coordination of voluntary muscle movement. "We found that the ATXN8/OS trinucleotide repeat expansion is the most prevalent cause of dominantly inherited ataxia in Finland confirming a previous observation." (PMID 34600502, 2021). "We found that mutations in ATXN8/OS, POLG and RFC1 are the most common genetic causes of ataxia in Finland." (PMID 34600502, 2021). "Expansion in ATXN8/OS results in the majority of dominant ataxias in Finland, while mutations in RFC1 and POLG are the most common cause of recessive ataxias." (PMID 34600502, 2021). "Expansion in ATXN8/OS (SCA8) was the most common cause of dominantly inherited ataxia, while the homozygous p.Trp748Ser mutation in POLG and the biallelic expansion in RFC1 were the most common causes of recessively inherited ataxia." (PMID 34600502, 2021). "Of all SCAs, SCA type 8 (SCA8) presents a molecular trait that distinguishes it from other dominant ataxias: its involving a CTG repeat expansion in the ATXN8OS (ataxin 8 opposite strand) gene and a CAG repeat expansion in the overlapping ATXN8 (ataxin 8) gene." (PMID 24040107, 2013).
Cerebellar atrophy (1 paper, 2014). Cerebellar atrophy is defined as a cerebellum with initially normal structures, in a posterior fossa with normal size, which displays enlarged fissures (interfolial spaces) in comparison to the foliae secondary to loss of tissue. "Spinocerebellar ataxia 8 (SCA8) is caused by expansion of CTG repeats in the ataxin 8 gene, and the resulting RNA gain of function produces cerebellar atrophy and coordination defects." (PMID 25303993, 2014).
ATXN8 also shares sentences with these, for which no sentence is quoted: amyotrophic lateral sclerosis (2 papers); myotonic dystrophy type 1 (2); nervous system diseases (2); benign adult familial myoclonic epilepsy (1); fragile X syndrome (1); frontotemporal dementia (1); Huntington disease (1); Huntington disease-like 2 (1); myotonic dystrophy type 2 (1); oculopharyngodistal myopathy 1 (1); tumor (1).